CD44 (CD44 molecule (IN blood group))
Diseases named in the same sentence as CD44 in open-access papers (continued):
Sharing a sentence is not in itself a finding about the gene and the disease.
cancer (continued). "Treatment with α-mangostin, Man-3DG, and Man-6DG markedly decreased the expression levels of cancer stemness regulators, including Nanog, Oct4, Sox2, CD44, and CD133, in the 3D tumorsphere-cultured Hep3B cells." (PMID 32516967, 2020). "Positive staining of the cancer stem cell marker CD44, the apoptosis marker Caspase-3, and the tumor suppressor p16 was observed across all PCC cultures." (PMID 31963309, 2020). "Another recent study confirmed that nicotine-treated MCF7 cells exhibited changes in cell structure, cellular motility (related to the relocation of F-actin) and an enhanced MCF7 CD44 + CD24- cancer stem cell population." (PMID 33203443, 2020). "HA-binding receptors, such as RHAMM and CD44, have been shown to be overexpressed on various cancer cell surfaces, further expanding the broad applicability of HA-based nanomedicines for active tumor-targeted drug delivery." (PMID 32489129, 2020). "The functional connection of alternative splicing to EMT and cancer metastasis was established through the study of the CD44 gene, which is alternatively spliced to generate two families of proteins, known as CD44v and CD44s." (PMID 31980632, 2020). "CD44 protein is an adhesion molecule that plays a role in cell migration and is overexpressed in different malignant tumors." (PMID 32756451, 2020). "Previously, it was reported that CD44, a transmembrane glycoprotein, is aberrantly expressed in several cancers and regulates cancer cell migration, invasion, and metastasis by interacting with extracellular ligands." (PMID 32098629, 2020). "Because CD44 can influence the metastasis and invasion of cancer cells, we next performed an in vivo experiment with CD44 knockout BCCs directly injected into the mouse through the tibia instead of the left ventricle." (PMID 32517712, 2020). "Herein, we aim at encapsulating the current understanding for CD44 structure and roles of CD44 during cancer initiation and progression." (PMID 33303029, 2020). "In brief, flow cytometry data showed that parental cancer cell lines and all investigated hybrid clones exhibited a rather identical CD44/CD24 expression pattern with more than 95% of CD44+/CD24−/low cells." (PMID 32430004, 2020). "Treatment of high-density cells with ZEB reduced expression of surface markers (such as CD133, CD44, EpCAM) and cancer stem cell properties as well as tumorigenesis, concomitant with upregulation of genes related to apoptosis and differentiation." (PMID 32466488, 2020). "In fact, ALDH1HIGH/CD44+ cancer cells have higher CSC features than the ALDH1low/CD44− cancer cells, illustrating that combining CSC markers can ameliorate CSC isolation specificity." (PMID 32280305, 2020). "While CD44 expression is almost undetectable on normal ovarian surface epithelium, the majority of epithelial ovarian carcinomas demonstrate high CD44 levels, which is correlated with disease progression, cancer stemness and resistance to therapy." (PMID 33335857, 2020). "Many of these effects result from HA-mediated activation of CD44, a pro-survival receptor enriched on the surface of cancer stem cells." (PMID 32774770, 2020). "In this study, we identified a novel inverse correlation between DAXX expression and that of the cancer stem cell markers CD44 and Oct4." (PMID 32203224, 2020). "Consistent with this, BSH-polyR was readily penetrated into CD44-expressing cells, whose properties were similar to those of cancer stem-like cells." (PMID 32977522, 2020). "Researchers have designed novel experimental drugs namely, Thiostrepton, whose pharmacological action consists of targeting the sonic Hedgehog signaling, Thiostrepton suppresses the population of CD44+/CD24− cancer stem cells (CSCs) of TNBC cell lines." (PMID 32245065, 2020). "Multiple stimuli-responsive nanomedicines based on HA have been developed for cancer therapy, such as an enzyme-responsive HA-based nanogel for drug delivery that is preferentially internalized by CD-44-overexpressing cancer cells." (PMID 32489129, 2020).
cancer (continued). "Numerous experimental and clinical studies are targeting pro-angiogenic isoforms of CD44, which are expressed by multiple cancer cell types." (PMID 33287867, 2020). "To date, several clinical trials have tested different CD44 targeting agents to generate a cancer-specific drug delivery system in the clinic." (PMID 33335857, 2020). "Lee and Jeong reported CD44 receptor-sensitive delivery of HA-Ce6-poly (L-histidine) copolymer nanoparticles against CD44-overexpressing cancer cells and their suppressive effect of tumor." (PMID 32580439, 2020). "Concerning CD24 and CD44, used to identify the cancer stem cells, MCCL-9 and MCCL-11 cells were CD24−/CD44+, whereas the MKL-1 cell line displayed a CD24+/CD44− profile." (PMID 32005907, 2020). "Several studies have reported that cancer cells that have undergone epithelial-to-mesenchymal transition possess more stem-cell-like characteristics, express an increased level of CD44, and require CD44v switch to CD44s isoform." (PMID 32391048, 2020). "CD44, an additional marker of colon CSCs, is a protein involved in cancer cell migration and matrix adhesion in response to a cellular microenvironment." (PMID 32729895, 2020). "Overall, although there is a large amount of literature on CD44 in cancer pathophysiology, the specific role of CD44 interaction with E-selectin has been poorly studied in vivo." (PMID 32793603, 2020). "CD44v6, the CD44 isoform mostly involved in cancer cell migration and invasion, has been identified as a functional biomarker of stemness and therapeutic target in colorectal cancer (CRC) tissues." (PMID 33227095, 2020). "The interaction between cancer cells and PMCs is mediated by the adhesion molecule CD44 expressed on the cancer cells and the hyaluronic acid expressed on PMCs surface." (PMID 33178597, 2020). "For the purposes of cytometry assays and sorting, we defined CCD133−/CD24+/CD9−as neuronal cancer cells, CD9+/CD44+/CD133− as astro-mesenchymal cancer cells, and CD9+/CD133+ as progenitor cancer cells." (PMID 32641768, 2020). "In particular, several isoforms of CD44 (CD44v) are up-regulated mostly by cancer cells and necessary for cell cancer invasion." (PMID 32708202, 2020). "Since HA, a major constituent of the ECM, is one ligand of CD44, it has been used in active targeting on CD44-overexpressing cancers, increasing drug uptake, and therapeutic efficacy." (PMID 32708833, 2020). "Overexpression of CD44 has been observed in many types of cancer, and the interaction between CD44 and ezrin, radixin, and moesin links the actin cytoskeleton to the plasma membrane and the extracellular matrix." (PMID 32679746, 2020). "CD44 expresses in a variety of cell types in humans, including embryonic stem cells, differentiated cells and cancer cells." (PMID 33303029, 2020). "In order to identify soluble CSC markers that can be used to predict cancer relapse, soluble CD44, CD44v6, and CD44v8-10 were further determined in CCA sera." (PMID 32039729, 2020). "CD44 inversely correlates with miR-16 expression, which appears downregulated in the serum from cancer patients in comparison with controls." (PMID 33224883, 2020). "To validate these results, we performed flow cytometry analysis of known surface molecules implicated in cancer progression including frizzled 7 (FZD7), CD44, MUC-1, and integrins α2, β4, αvβ3, β3, and α4." (PMID 32352029, 2020). "Here, we assessed the transcriptomic profile of our spheroids by analysing some key genes involved in the EMT/migration process (VIMENTIN), cancer stem cells phenotype (CD44), cytokine secretion (TGF-β1) and proliferation (Ki67), respectively." (PMID 32576846, 2020). "On the other hand, many studies have investigated the DDS incorporating hyaluronic acid or chondroitin sulfate as a ligand to target CD44-overexpressing cancer cells." (PMID 32133350, 2020). "IGF2BP1 can increase the stability of CD44 mRNA and promotes cell adhesion and invadopodia formation in cancer cells." (PMID 31897227, 2020).
cancer (continued). "Recent studies have suggested that in the development of HCC, CD44+ cells were entwined with the genetic processes involved in cancer invasion and metastasis." (PMID 33062675, 2020). "CCL5 is known to enhance binding of leukocytes and T cells via CD44 signaling, an adhesion molecule common in many cancers." (PMID 32252260, 2020). "Compared with those before NAC, the expressions of N-cadherin and CD44 were significantly downregulated in cancer tissues after NAC (P < 0.05)." (PMID 33282946, 2020). "TW-1 expressed various markers that are unique in stem cell, such as CD133, GSTP1, CD44, and EpCAM, which was identified as a cancer cell line with progenitor or stem cell-like properties." (PMID 33322441, 2020). "CD44 is also included in many of the pathways found to be significantly altered between the cancer cells and epithelial cells and between the cancer cells and redirected cells including the EMT, TNFα_via_NFkB, apoptosis, IL6_JAK_STAT3 and IL2_STAT5 pathways." (PMID 32774772, 2020). "CD44 is a transmembrane glycoprotein that was one of the first molecules identified on GC stem cells and is now known to be a marker for cancer stem cells (CSCs)." (PMID 32183503, 2020). "As previously reported, the skipping of CD44 exon v8 leads to increase in the chemosensitivity of cancer stem cells." (PMID 33266296, 2020). "Heparan sulfate and CD44, which are responsible for growth factor signaling, are overproduced in cancer cells." (PMID 32645959, 2020). "Retinoic acid (RA) can reduce the ALDH activity and CD44 expression, thus affecting cell proliferation, cancer invasiveness and sensitivity to various chemotherapy drugs." (PMID 32293355, 2020). "CD44 is overexpressed in various cancers; however, it is also expressed on non-cancer cells in the TME, including some populations of activated lymphocytes." (PMID 33322807, 2020). "CD44 represents a common biomarker of cancer stem cells, and promotes epithelial-mesenchymal transition." (PMID 33303029, 2020). "Activation of CD44 in cancer cells promotes stemness, drives sphere formation, and increases invasion and migration." (PMID 33330449, 2020). "For example, hyaluronic acid (HA) can recognize CD44 receptors on the cancer cells and then they can be used to detect CD44-overexpressing cancer cells through conjugation with Ce6." (PMID 32580439, 2020). "The pleiotropic roles of CD44 in carcinoma potentially offering new molecular target for therapeutic intervention." (PMID 33303029, 2020). "Hepatocytic (HNF4), EMT (Twist, Snail), and cancer stem cell markers (CD44, EpCAM, CK19, Sox9) were simultaneously expressed in these cells." (PMID 31726709, 2019). "To this end, we analyzed the typical cancer stem cell traits such as clonogenic and spheroid formation abilities in the double positive CD44/CD133 cell subpopulations compared with the single positive subpopulations obtained as result of OGT inhibition." (PMID 31139149, 2019). "Recently, in numerous resistant cancers including pancreatic, breast, ovarian, prostate, colorectal cancers and neuroblastomas; CD44 has been identified as an interesting marker of cancer stem cell like cells." (PMID 35582577, 2019). "Our study indicated that BRM270 presents strong inhibitory effect on CD44+ PDAC cells via induction of cancer cell death, inhibitions of migration, invasion, and wound healing behaviors." (PMID 31049070, 2019). "Reduction of CD44 and CD133 expression is correlated with loss of mesenchymal properties and acquisition of the epithelium-like phenotype in cancer cells associated with improvement of chemotherapy drug sensitivity." (PMID 31139022, 2019). "The harmlessness of HA, allied with its effective targeting capability, encouraged its employment to selectively internalize HA-functionalized materials (HA-materials) in CD44-overexpressing cancer cells via receptor-mediated endocytosis." (PMID 30804375, 2019).
cancer (continued). "Due to the specific targeting ability of HA, these NPs were preferentially internalized into CD44-over-expressing SCC7 cancer cells." (PMID 31266194, 2019). "In particular, this polysaccharide can be specifically recognized by membrane receptors (such as CD44) present on most mammalian cells and many cancer cells." (PMID 31311150, 2019). "The population of CD44 positive (CD44+) GC cells, recognized as cancer stem cell (CSC) typical markers, was significantly increased as detected by flow cytometric analysis." (PMID 30742067, 2019). "In ovarian cancer, the killing of CD44+ CD117+ cancer-initiating cells by CXCR4 antagonist expressed-oncolytic vaccinia virus infection was reported." (PMID 30841635, 2019). "HT29 cell line was identified as cancer stem-like cells with the high expression of CSCs markers CD44 and CD24." (PMID 31640758, 2019). "We have demonstrated that inhibiting the HH pathway is related to a reduction of cells with the cancer stem cell related phenotype (CD44+/CD24−), less sphere forming capability and more radiosensitivity." (PMID 31200527, 2019). "Stem-like cells acquire a more complete EMT molecular profile, and are reported to express the cancer stem/progenitor cells marker CD44, which plays an important role in inducing EMT and/or in maintaining the mesenchymal phenotype in PCa." (PMID 30754655, 2019). "Among these molecules, we emphasize the increased expression of CD44 which was previously assigned as cancer stem cell marker and of mTOR, a characteristic indicator of the engagement of the PD-1:PD-L1 pathway." (PMID 31681332, 2019). "In mechanistic studies, we find that rhPRG4 suppresses TGFβ-induced invasiveness of cancer cells by inhibiting the downstream hyaluronan (HA)-cell surface cluster of differentiation 44 (CD44) signalling axis." (PMID 31361756, 2019). "CD44(+) GC CSC cell numbers were decreased by cisplatin combined with RHOA signaling inhibitors; A cancer hallmark term, resisting cell death (cancer stem-like cells, CSCs) associated." (PMID 31156701, 2019). "The improved cytotoxic activity of these NPs was proven in CD44-over-expressing HCT-116 cancer cells." (PMID 31266194, 2019). "HA binds CD44, which is often overexpressed on the surface of cancer cells and is believed to be a representative marker of cancer stem cells." (PMID 31072061, 2019). "miR-302a restored CTX responsiveness by directly suppressing CD44, which induced cancer stem cell (CSC)-like properties and activated EGFR-dependent MAPK and AKT signaling." (PMID 31754405, 2019). "We identified CD87, CD44, CD49b, CD95, and Ly-6C as cancer-associated fibroblast cell surface markers, while CD39 was identified to mark normal fibroblasts from healthy tissues." (PMID 31428583, 2019). "These Apt1-functionalized liposomes showed higher selectivity and uptake by CD44+ cancer cell lines compared to the CD44− cell line." (PMID 31861277, 2019). "Several CSC marker molecules, such as CD166, epithelial cell adhesion molecule (EpCAM) and CD44, have been identified and have become useful markers in human cancers." (PMID 30788285, 2019). "Correspondingly, the inhibition of CD44 has the ability to attenuate the malignant phenotype, slowing cancer progression and reversing therapy resistance." (PMID 31528214, 2019). "miR-302a restored CTX responsiveness by suppressing CD44-induced cancer stem cell-like properties and EGFR-mediated MAPK and AKT signaling." (PMID 31754405, 2019). "miR-34a inhibits cancer stemness via targeting CD44; miR-34a expression inhibits TGF-β-induced EMT and downregulates Snail, Slug and ZEB1 as well as the stemness factors (BMI1, CD44, CD133, OLFM4 and c-MYC)." (PMID 30885232, 2019). "As CD44 is a known cancer stem cell marker, the expression levels of CD44 in HCC cells were determined." (PMID 31888604, 2019). "The transmembrane glycoprotein CD44 is another commonly used cell surface marker of cancer stem cells." (PMID 31273285, 2019).
cancer (continued). "Cancer stem cells in breast cancer have two different forms, the mesenchymal-like cancer stem cells are CD44+/CD24−, while the epithelial-like cancer stem cells are aldehyde dehydrogenase 1 family, member A1 (ALDH1) positive." (PMID 30934972, 2019). "We quantified by an ELISA-based technique specific proteins of cancer-derived exosomes (CD44,CD44v6,EpCAM,CD9,CD81,Tspan8,Integrin α6,Integrin β4,CD24,CXCR4)." (PMID 31048929, 2019). "The CD44– cells that are more susceptible to the first-line chemotherapy are eliminated, while the more chemoresistant CD44+ cells give rise to one or more different cancer cell populations that resist chemotherapy currently available." (PMID 31366178, 2019). "ERK activation drives cell proliferation, migration, and invasion through anti-apoptotic and proliferative signaling pathways, and ERK activation modulates cancer aggressiveness by the regulation of CD44 expression." (PMID 31878324, 2019). "CD44 expression is upregulated in the microenvironment that promotes cancer progression and metastasis." (PMID 31480284, 2019). "Granzyme B was delivered to CD44-overexpressing cancer cells on the self-assembled hyaluronic acid-epigallocatechin gallate conjugates, functionalized with linear polyethyleneimine (PEI)." (PMID 30943985, 2019). "It has been shown that the standard isoform of CD44 (CD44s) is associated with an EMT phenotype of PDAC cells, cancer invasiveness, and gemcitabine resistance." (PMID 31108941, 2019). "HA links to cellular receptor CD44 and their interaction in the high-fat diet in mice promoted cancer progression and therapy resistance in different types of cancer, including in HCC11,12." (PMID 30858465, 2019). "The current findings revealed that CD44 is a surface marker of cancer stem cells (Yan, Zuo & Wei, 2015)." (PMID 31523525, 2019). "The impact of the expression of CD44, CD44v6, and CD44v9 on the prognosis of patients with advanced cancer has not been fully understood." (PMID 30788285, 2019). "CD44 can be a useful target in cancer treatment because of its aberrant overexpression in cancer cells." (PMID 31689930, 2019). "In fact, the expression of CD44 in different cancer cells has been reported to be regulated by NF-ĸB, a signaling pathway that is rapidly activated in gastric epithelial cells upon H. pylori infection." (PMID 30884828, 2019). "Although CD44 is expressed in healthy tissue, it is often up-regulated in different cancer types, including PDAC." (PMID 30650521, 2019). "GNRs@mSiO2–HA–RGD (RGD: Arginine–glycine–aspartate) nanocarriers have been synthesized for targeting CD44- and integrin receptor-over-expressing cancer cells (SKOV-3)." (PMID 31266194, 2019). "The MLL1‐ZC3H13 chimera consistently increased the expression of a cancer stem cell marker (CD44); in addition, we detected potential collateral lethality between DOT1L and MLL1 fusions." (PMID 30548174, 2019). "CD44, a cell adhesion molecule expressed on cancer tissue, is the principal cell surface receptor for extracellular matrix glycosaminoglycan hyaluronan (HA)." (PMID 30691317, 2019). "H. pylori has been previously shown to target and expand the CD44+ gastric stem cell compartment, while inhibition of CD44 blocked proliferation and cancer progression in H. pylori-infected gerbils." (PMID 30884828, 2019). "SA is an abundant globular blood protein; we recently introduced the potential of HA-SA Maillard conjugates for targeting CD44-overexpressing cancers." (PMID 31060303, 2019). "We treated cancer cells with ivermectin and analyzed the CD44+/CD24−-expressing subpopulation to examine the effect of ivermectin." (PMID 31658701, 2019). "Intriguingly, mesothelial cells facilitate cancer stemness properties in spheroids of OC cells, including increasing CD44 expression, suggesting a positive feedback loop in adhesion step between mesothelium and floating OC cells." (PMID 31277278, 2019).